AOX1 (aldehyde oxidase 1)
Diseases named in the same sentence as AOX1 in open-access papers (continued):
Sharing a sentence is not in itself a finding about the gene and the disease.
Cirrhosis (1 paper, 2021). A chronic disorder of the liver in which liver tissue becomes scarred and is partially replaced by regenerative nodules and fibrotic tissue resulting in loss of liver function. "And AOX1's expression was remarkably related to histological differentiation, satellite lesions, and vascular cancer embolus while UGT1A4's expression was remarkably related to histological differentiation, satellite lesions, pN, and cirrhosis." (PMID 34337056, 2021).
colon cancer (1 paper, 2012). "Aberrant DNA hypermethylation of the AOX1 promoter region was recently reported in colon cancer and PCa." (PMID 23119026, 2012).
colorectal cancer (1 paper, 2021). A primary or metastatic malignant neoplasm that affects the colon or rectum. "In colorectal cancer, downregulation of AOX1 has been reported to be a consequence of AOX1 hypermethylation." (PMID 34073600, 2021). "While the majority of studies convincingly show that downregulation of AOX1 is related to many types of cancer, a recent study of AOX1 in colorectal cancer showed that its high expression promotes invasion, and inhibits apoptosis, via ROS production." (PMID 34073600, 2021).
esophageal carcinoma (1 paper, 2013). A primary or metastatic malignant neoplasm involving the esophagus. "ADH1B and AOX1 are involved in the metabolism of nicotine, with the former gene implicated in the risk of esophageal carcinoma." (PMID 24134934, 2013).
kidney stone (1 paper, 2024). "Interestingly, we observe a similar transcriptional up-regulation of Aox1 and down-regulation of Uro, MFS2 and Eglp2, as well as similar phenotypes, i.e., elevated levels of uric acid, kidney stone formation and bloating, in both Yki flies and flies with activated PDGF/VEGF signaling in PCs." (PMID 38336808, 2024).
lung adenocarcinoma (1 paper, 2022). A carcinoma that arises from the lung and is characterized by the presence of malignant glandular epithelial cells. "As well, the Aox1 genewas reported as an NRF2 binding site in the Keap1-mutated Lung adenocarcinoma patients." (PMID 35180880, 2022).
lung carcinoma (1 paper, 2022). "In support of the proposition that AOX1 inhibition may increase the NAD+ level comes from the results of screening 304 active compounds, covering a broad range of oncology targets, to evaluate their effect on the NAD+ level in A549 lung cancer cells." (PMID 35457123, 2022).
melanoma (1 paper, 2021). A malignant, usually aggressive tumor composed of atypical, neoplastic melanocytes. "We observed highly elevated AOX1 gene expression in LATS1 knocked down cells, both in melanocytes and melanoma cell line." (PMID 33803640, 2021).
metastatic tumors (1 paper, 2012). "Our analysis also associated promoter methylation with reduced AOX1 gene expression in PCa samples compared with normal tissues and further decreased expression of this gene in metastatic tumor samples." (PMID 23119026, 2012). "The expression of ALDH2 and ALDH3A2 were significantly down-regulated in primary tumor samples and further down-regulated in metastatic tumors, similar to AOX1 expression." (PMID 23119026, 2012).
Obesity (1 paper, 2016). Accumulation of substantial excess body fat. "In fact, sex controls the levels of liver AOX3 and WADT AOX1 in knock-out mice, whereas it does not affect resistance to obesity." (PMID 27456060, 2016).
osteoporosis (1 paper, 2022). A condition of reduced bone mass, with decreased cortical thickness and a decrease in the number and size of the trabeculae of cancellous bone (but normal chemical composition), resulting in increased fracture incidence. "Raloxifene, a prescription drug for the treatment of osteoporosis, is a potent AOX1 inhibitor in clinically relevant doses." (PMID 35457123, 2022).
sarcoma (1 paper, 2020). A usually aggressive malignant neoplasm of the soft tissue or bone. "Conversely, the expression of another mesenchymal gene, AOX1, which was downregulated during serial xenotransplantation, significantly correlates with a better prognosis in sarcoma patients." (PMID 31941033, 2020).
thyroid cancer (1 paper, 2020). "Genes related to cytoprotection and antioxidant response (e.g., Gsta3, Gstm1, Nqo1, Gpx2), as well as the H2O2-producing gene Aox1 that is usually decreased in thyroid cancers, were all downregulated in thyroids of KO mice, as found previously in other tissues." (PMID 32961913, 2020).
tumor (22 papers, 2012 to 2026). "AOX1, a phase I xenobiotic enzyme with a role in oxidation of drugs and toxicants, has also been associated with impairment of tumor growth and sensitization to cancer drugs." (PMID 39488528, 2024). "ccRCC tissues have significantly lower AOX1 mRNA and protein expression than normal kidney tissues, and lower expression in tumor tissues was associated with worse overall survival in ccRCC patients." (PMID 34290740, 2021). "In NSCLC experimental models we have found that G9a/DNMT1 inhibition impairs cancer cell malignancy and reduces tumor growth, an effect that is mediated by enzymes AOX1 and SCARA5." (PMID 39488528, 2024). "Many of these (DLK1, GAB2, BOLA2B, AOX1 and AGER) were closely related to cell proliferation and tumor progression, and associated with poor prognosis in HCC." (PMID 35331184, 2022). "The results showed that a total of 181 samples had tumor mutation burden (TMB), of which OGDHL gene had the highest mutation frequency, followed by AOX1 and AOC1." (PMID 36185621, 2022). "According to the previous literature, the positive prognostic values of ZNF185, SRD5A2, and AOX1 are expressed in normal tissues than in tumors, but their methylation levels in tumor tissues are higher than those in normal tissues." (PMID 35813821, 2022). "Decreased AOX1 mRNA and protein levels in ccRCC tissues compared with normal tissues suggest a tumor-suppressive role of AOX1." (PMID 34290740, 2021). "Using data from The Cancer Genome Atlas (TCGA), we show that this aberrant promoter methylation led to downregulation of AOX1 in tumor tissues." (PMID 33450964, 2021). "GGCT expression was significantly upregulated in tumor tissues, while AOX1, NT5E, PPP1R12A, and PTGS2 were significantly downregulated compared to normal tissues in the TCGA cohort." (PMID 34484299, 2021). "One of identified genes, AOX1, which was previously suggested as a methylation biomarker for PCa, showed significant hypermethylation for multiple probes in tumor tissue." (PMID 33450964, 2021). "And this effect is not restricted to ccRCC but universally exists in many other types of tumors, considering the significantly diminished expression of AOX1 in more than half of the tumor types in TCGA database." (PMID 34290740, 2021). "Next, we compared AOX1 mRNA expression in 31 different types of tumor samples and normal tissue samples using GEPIA." (PMID 34290740, 2021). "Taking the in vitro and in vivo results together, it was shown that Txnip, Aox1, Per3 and Ypel3 were consistently upregulated in both tumor lines and Acat2, Clspn and Ercc6l were downregulated." (PMID 33407762, 2021). "Meanwhile, the expression of AOX1 was detected to be lower in various tumor samples than in normal samples." (PMID 34568357, 2021). "One of identified genes, AOX1, showed significant hypermethylation for multiple probes in tumor tissue." (PMID 33450964, 2021). "We studied the association between tumor pathology and the expression profile of seven phase I and II drug metabolizing genes (CYP1A1, CYP1B1, ALDH3A1, AOX1, GSTP1, GSTT1 and GSTM3) and some of their proteins." (PMID 26580399, 2015). "After reviewing these data, we arbitrarily set a cut-off level of 0.3 for assigning AOX1 promoter methylation to distinguish tumor from normal tissue." (PMID 23119026, 2012). "This plot indicated the almost all of the tumor samples had greater than the mean methylation value of 0.3 in the AOX1 promoter, while paired adjacent normal tissue had relatively lower methylation (less than mean methylation value 0.3)." (PMID 23119026, 2012). "Therefore, the expression of Il6, Nos2, Ccl2, Spp1, Tnf, Acat2, Aox1, Crem, Gls2, Per3, Pink1, Txnip, and Ypel3 was examined in acidosis upon simultaneous transfection with microRNA mimics or antagomirs in two tumor lines in vitro and in vivo." (PMID 38069241, 2023).
tumor (continued). "Overexpression of AOX1 significantly reduced the proliferation and migration of PCa cells, suggesting that the anti-tumor effect of AOX1 may be attributed to its impact on oxidative stress." (PMID 37583929, 2023). "Moreover, we conducted experimental validation and discovered that AOX1 functions as a tumor suppressor in PCa by inducing oxidative stress." (PMID 37583929, 2023). "The relationship between AOX1 and cancer is ambiguous, depending on tumor type." (PMID 33803640, 2021). "One hundred eight genes including AOX1 were differentially methylated in tumor samples." (PMID 33450964, 2021). "Specifically, some genes were significantly modulated in all three tumors in the same way: AOX1, ENPP3, and NMRK2 were down-modulated in tumor specimens, whereas PARP1 was up-regulated." (PMID 38254798, 2024). "AOX1, ENPP3, and NMRK2 were down-modulated in all analyzed tumor specimens, whereas PARP1 was up-regulated." (PMID 38254798, 2024). "Beyond the well-established tumor marker PARP1, AOX1 can be a potential common therapeutic target for SCC treatment." (PMID 38254798, 2024). "In contrast, reduced expression of AOX1 is detected in HCC cells and is highly correlated with higher tumor stage, distant metastases or positive lymph node status." (PMID 32296612, 2020). "Among the DE genes involved in inflammatory response, solely one gene (AOX1) was found to be upregulated in all four cell types while MGLL was the only gene upregulated in the immortalized keratinocytes and HPV+ tumor cells." (PMID 23702334, 2013). "Aberrant DNA methylation of two genes, AOX1 and SPON2, were confirmed via bisulfate sequencing, with most of the respective CpG sites showing significant differences between tumor samples and normal tissues." (PMID 23119026, 2012). "However, NMRGs with significant AUC values (AOX1, SIRT3, NMRK1, PARP1) were differentially expressed among tumor stages." (PMID 38254798, 2024). "Both SCARA5 and AOX1 showed hypermethylation in tumor samples compared to non-malignant lung samples." (PMID 39488528, 2024). "The hypothesis is that the downregulation of LATS1 enhances ROS production, promoting an intrinsic hypoxia state with elevated AOX1 expression, which upregulates cancer stem cell marker CD133 resulting in enhanced tumor growth." (PMID 33803640, 2021). "Finally, we illustrated that the effect of AOX1 as a tumor suppressor gene is not restricted to ccRCC but universally exists in many other cancer types." (PMID 34290740, 2021).
cancer (21 papers, 2016 to 2025). A tumor composed of atypical neoplastic, often pleomorphic cells that invade other tissues. "AOX1 catalyzes the oxidation of a variety of endogenous and exogenous aldehydes and N-heterocyclic aromatic compounds, and the epigenetic loss of AOX1 leads to metabolic deregulation and promotes cancer progression." (PMID 36300097, 2022). "In another stratification analysis by family history of cancer, AOX-1 hypermethylation was associated with risk of CRC regardless of the presence of a family history of cancer." (PMID 27453436, 2016). "The AOX1 gene, contributing to improved diagnostic sensitivity and related to poor prognosis in PC patients, can be used as an independent risk factor for predicting cancer recurrence in PC." (PMID 31288850, 2019). "In the ccRCC patients, reduced expression of AOX1 predicts worse overall survival, and the predictive value is further supported by the target–disease association analysis of AOX1, which identified more than 20 kinds of cancers as its potentially relevant diseases including ccRCC." (PMID 34290740, 2021). "We then verified that SCARA5/AOX1 promoters were hypermethylated in tumors and cancer cell lines and that, upon treatment of the cells with 5-azacitidine, both genes were re-expressed." (PMID 39488528, 2024). "To conclude, AOX1 is abundant in normal kidney tissue, and it is downregulated not only in ccRCC but also in many other cancers." (PMID 34290740, 2021). "Downregulation of AOX1, in this type of cancer, was accompanied with an accumulation of kynurenine, as a consequence of activation of the kynurenine pathway." (PMID 34073600, 2021). "Thioridazine, another AOX1 inhibiting drug, induces cell death and inhibits self-renewal in a variety of cancer cells." (PMID 34073600, 2021). "Recently, AOX1 has been uncovered to participate in the development and progression of a series of cancers." (PMID 33135729, 2020). "Overall, our results suggest that the anti-cancer effect of AOX1 may be mediated through the activation of oxidative stress." (PMID 37583929, 2023). "AOX1, a cancer-related gene encoded Aldehyde Oxidase 1 and mutated in 30% of our GLP cohort, was found to play an oncogenic role in cancer progression through its epigenetic changes, but the relationship between its mutations and cancer have not been well reported." (PMID 36450891, 2023). "Our future research may focus on the molecular mechanism for AOX1’s dysregulation in ccRCC and how its expression impacts the behavior and biology of cancer cells by using transgenic mouse and cell lines." (PMID 34290740, 2021). "In addition, we profiled AOX1 expression patterns in various normal human tissue and many other different cancer types and explored the AOX1-related disease spectrum." (PMID 34290740, 2021). "In addition, we profiled AOX1 expression patterns in RNA and protein levels in distinct normal and cancerous tissues and found consistent downregulation of the AOX1 gene in many other cancer types." (PMID 34290740, 2021). "On the contrary, in AOX1−/−APCmin/+ mice, the expression of CD133 in cancer tissue was significantly decreased, and the survival rates were increased." (PMID 34073600, 2021). "Aldehyde oxidase 1 (AOX-1) was found to be down-regulated and hypermethylated in CRC tissues, suggesting a potential functional role of this gene in cancer development." (PMID 27453436, 2016). "However, CM-272 reduced levels of the transcriptional repression mark H3K9me2 bound to the promoter regions of SCARA5 and AOX1, which suggests that, at least in NSCLC cancer cells, this may constitute a main mechanism of activity." (PMID 39488528, 2024). "Systematic exploration of NAM and its metabolites MNAM, 2PY, and 4PY in cancer, related to the expression of not only NNMT, but also NAMPT (the rate-limiting enzyme in NAD+ salvage pathway) and AOX1 (oxidizes MNAM to 2-PY and 4-PY), may provide a better insight into their function." (PMID 34073600, 2021).
infection (9 papers, 2020 to 2025). The state of being infected such as from the introduction of a foreign agent such as serum, vaccine, antigenic substance or organism. "Levels of AOX1 increase in mouse liver following infection suggesting a role in immune response by stimulating host immunity, inflammation and coagulation." (PMID 34082698, 2021). "Similar to Tdo2, the genes Acmsd and Aox1 were significantly upregulated in liver tissue in the innate phase of infection." (PMID 33045014, 2020). "Lastly, enhanced virulence of C. albicans that is observed for wild-type cells under high iron was lost when fungal cells lacking AOX1/2 were used for murine infection." (PMID 37929974, 2023). "Thus, Acmsd and Aox1 might be regulated by other non-epithelial cell types in the liver at this time point after infection." (PMID 33045014, 2020).
myopathy (1 paper, 2024). A disease of the muscle in which the muscle fibers do not function properly. "The top five up-regulated genes in general myopathy are MGST1, AOX1, FASN, PRKCD, and CHRNA1, which have been rarely reported in previous myopathy studies." (PMID 38600180, 2024). "The genes featured for general myopathy indeed showed relatively higher expression trend in the myopathy muscles: MGST1 (RQ 10.34/2.09, p = 0.02), AOX1 (RQ 4.53/2.41, p = 0.42), FASN (RQ 3.75/1.75, p = 0.10), PRKCD (RQ 2.10/1.23, p = 0.19)." (PMID 38600180, 2024). "We selected four up-regulated genes for general myopathy (MGST1, AOX1, FASN, PRKCD), CD163 for IBM, and CYP4B1 for titinopathy, aiming to validate their actual expression in our local muscles." (PMID 38600180, 2024).
AOX1 also shares sentences with these, for which no sentence is quoted: Molybdenum cofactor deficiency (3 papers); xanthinuria type I (3); rectal cancer (2); renal failure (2); sulfite oxidase deficiency (2); viral infection (2); amyotrophic lateral sclerosis (1); anemia (1); anxiety disorder (1); chronic pancreatitis (1); depression (1); glioblastoma (1); head and neck squamous cell carcinoma (1); Insulin resistance (1); iron deficiency (1); lipid metabolic disorder (1); liver cancer (1); liver fibrosis (1); malaria (1); mastitis (1); medullary thyroid cancer (1); meningeal tumors (1); motor neuron disease (1); non-small cell lung carcinoma (1); Onset (1); rheumatoid arthritis (1); steatosis (1); Stillbirth (1); thyroid tumor (1); triple-negative breast carcinoma (1).
A further 2 diseases each share a sentence with AOX1 in 1 paper.